AURKA (aurora kinase A)
Diseases named in the same sentence as AURKA in open-access papers (continued):
Sharing a sentence is not in itself a finding about the gene and the disease.
gastric cancer (continued). "Among the downregulated microRNAs in gastric cancer, we found miR-4715-3p had a predictable target score of 86% for AURKA 3′UTR." (PMID 31740746, 2019). "The present study has investigated the clinicopathological significance of AURKA expression in gastric cancer and the correlation with androgen receptor." (PMID 31871591, 2019). "Inhibition of AURKA led to strong cytotoxicity to gastric cancer cells with cytoplasmic p27 degradation and Bax cleavage, which were caused by activating the calpain pathway." (PMID 30013101, 2018). "AURKA overexpression has been shown to stabilize β-catenin levels and thereby activating Wnt signalling in gastric cancer cells by phosphorylating the negative regulator of β-catenin, GSK3B18,19." (PMID 29760449, 2018). "To further investigate the relationship between AURKA and p27, we analyzed AURKA and p27 expression by immunohistochemistry (IHC) in gastric cancer tissue samples with matched adjacent tissues from 80 patients." (PMID 30013101, 2018). "Our results suggest that the higher expression of AURKA and p27 in gastric cancer play an important role in gastric cancer carcinogenesis." (PMID 30013101, 2018). "It is noteworthy that endogenous FBXL7 mRNA and protein levels were low in AURKA wild-type gastric cancer cells; however, both FBXL7 mRNA and protein levels reached detectable levels only after AURKA depletion." (PMID 28218735, 2017). "In this study, we demonstrate that AURKA promotes acquired and de novo resistance to cisplatin in in vitro and in vivo gastric cancer cell models." (PMID 28417568, 2017). "In vivo tumor xenografts data corroborated these results and confirmed that inhibition of AURKA was sufficient to overcome CDDP resistance in gastric cancer." (PMID 28417568, 2017). "Basal levels of FBXL7 mRNA and protein were low in gastric cancer cells and only became detectable after AURKA depletion." (PMID 28218735, 2017). "Overexpression of AURKA exacerbated gastric cancer drug resistance through upregulating the expression of the anti-apoptotic protein Survivin." (PMID 28218735, 2017). "Clinicopathologic correlation analysis showed that AURKA positivity was strongly correlated with a number of gastric cancer clinical features." (PMID 28218735, 2017). "The results indicate that inhibiting AURKA can be an effective therapeutic approach to target CDDP‐resistant gastric cancer cells." (PMID 28417568, 2017). "We first assessed the relationship between AURKA and gastric cancer prognosis by immunohistochemical analysis." (PMID 28218735, 2017). "Inhibition of AURKA also reduced growth of xenograft tumors from human gastric cancer cells in mice and reversed the development of gastric tumors in Tff1-/- knockout mice." (PMID 28350359, 2017). "A small selective inhibitor of AURKA MLN8237 (Alisertib) suppressed NF-κB activity in human gastric cancer samples and mouse epithelial cells, and reduced expression of NF-κB target genes that regulate inflammation and cell survival." (PMID 28350359, 2017). "Here we found that AURKA was highly overexpressed in gastric cancer and inversely correlated with disease prognosis." (PMID 28218735, 2017). "The human AURKA gene maps to chromosome region 20q13.2, which is frequently amplified in different malignancies, including gastric cancer." (PMID 28218735, 2017). "In this study, we addressed this question and found that AURKA and Survivin cooperated in gastric cancer development and had a decisive role in resistance to DNA-damaging agents and poor cancer prognosis." (PMID 28218735, 2017). "To confirm further that AURKA mediated Survivin upregulation, we performed immunohistochemistry of 62 pairs of gastric cancer specimens and found that AURKA expression was positively correlated with Survivin expression (r=0.402; P<0.01)." (PMID 28218735, 2017). "To this end, we studied the expression of AURKA protein in a large cohort of 240 gastric cancer patients and found that 172 (71.7%) subjects had high AURKA expression." (PMID 28218735, 2017).
gastric cancer (continued). "Recently AURKA has been extensively investigated in different neoplasms, including breast, ovarian, colon, liver, pancreas, bladder, and gastric carcinomas." (PMID 28187748, 2017). "Prognostic assessment was not the focus of the present study as we aimed to experimentally demonstrate the in silico link between AURKA and Wnt signaling in gastric cancer at the gene expression level." (PMID 26778597, 2016). "AURKA is a crucial candidate gene for gastric cancer and is relevant to the Wnt/β-catenin and PI3K/Akt signaling pathways." (PMID 27121204, 2016). "Our gastric cancer candidate gene, AURKA (Fisher's exact test; P=6.83×10−6), was markedly differentially expressed in experiments studying gastric cancer with normal gastric mucosa." (PMID 27121204, 2016). "In patients with gastric cancer, AURKA gene expression was detected in all of the tumor samples, and also in all tumor‐adjacent and tumor‐distant mucosa biopsies." (PMID 26778597, 2016). "In summary, our findings indicate that rhBNP-2 suppresses gastric cancer cell proliferation by inhibiting β-catenin and c-Myc with AURKA and AURKB expression to regulate inhibition of the cell cycle." (PMID 27636990, 2016). "In conclusion, this is, to our knowledge, the first study showing an association of AURKA and RACGAP1 in gastric cancer as well as a connection with Wnt‐signaling components." (PMID 26778597, 2016). "In summary, AURKA is a potential therapeutic target in gastric cancer and induces EMT through histone methylation." (PMID 27121204, 2016). "To verify the role of AURKA, we established a subcutaneous gastric carcinoma model using MGC-803 cells." (PMID 27121204, 2016). "The findings collectively indicate that high levels of AURKA expression could serve as an independent predictor of poor prognosis in gastric cancer patients." (PMID 39683707, 2024). "AURKA promoted gastric cancer cell growth by regulating GSK-3β." (PMID 38287009, 2024). "Furthermore, chebulagic acid markedly suppressed the tumorigenic capabilities of gastric cancer cells and hindered the AURKA/β-catenin/Wnt pathway." (PMID 39683707, 2024). "AURKA was aberrantly expressed in many cancer cells, especially in gastric cancer." (PMID 34895070, 2021). "AURKA expression correlates with overall survival of gastric cancer patients." (PMID 31871591, 2019). "Moreover, our study provided evidence elucidating a novel promising marker, simultaneous evaluation of AURKA and AR expression, which properly predict prognosis of gastric cancer patients." (PMID 31871591, 2019). "In group 1, the majority of adjacent tissues had weak expression of AURKA (31/80) compared with that of tumor tissues (6/80); however, in the other groups, the majority of gastric cancer tissues (74/80) had stronger expression of AURKA compared with that of adjacent tissues (49/80)." (PMID 30013101, 2018). "Thus, our study provides the first piece of appealing evidence supporting the notion that AURKA is an attractive target for the development of gastric cancer therapeutics." (PMID 30013101, 2018). "Finally, we found that the positive correlation between AURKA and p27 in advanced gastric cancer patients." (PMID 30013101, 2018). "Importantly, high expression of AURKA and p27 exhibited a positive linear correlation in the gastric cancer tissue samples (r = 0.248, P = 0.027)." (PMID 30013101, 2018). "In conclusion, our data suggest that AURKA limits Survivin ubiquitylation and degradation in gastric cancer and provide a novel therapeutic target to promote the efficacy of DNA-damaging agent in gastric cancer." (PMID 28218735, 2017).
gastric cancer (continued). "In the present study, we found that AURKA could override DNA-damaging agent-induced cell death in gastric cancer cell lines, resulting in the development of drug resistance which was at least partially mediated through Survivin stabilization." (PMID 28218735, 2017). "To confirm our hypothesis that AURKA modulates Survivin expression in gastric cancer cells, we depleted endogenous AURKA in gastric cancer cells and examined AURKA and Survivin protein expression." (PMID 28218735, 2017). "This led us to speculate that FBXL7 was a potential tumor suppressor gene and its expression was repressed by AURKA in gastric cancer." (PMID 28218735, 2017). "Taken together, our data suggest that AURKA restricts Survivin ubiquitylation and degradation in gastric cancer to promote drug resistance and hence the AURKA–Survivin axis can be targeted to promote the efficacy of DNA-damaging agents in gastric cancer." (PMID 28218735, 2017). "Our study indicated that the limited chemotherapy efficacy might be due to high expression levels of AURKA in gastric cancer." (PMID 28218735, 2017). "Herein, we investigated the role of AURKA in CDDP resistance in gastric cancer." (PMID 28417568, 2017). "Targeting AURKA could be an effective therapeutic approach to overcome CDDP resistance in refractory gastric cancer and possibly other cancer types." (PMID 28417568, 2017). "We need more efforts to research whether inhibition of AURKA could damage gastric cancer's drug resistance by reverse EMT." (PMID 27121204, 2016). "Additionally, the mechanism underlying the effect on histone modification by AURKA was not investigated, and we need to identify more downstream genes related to AURKA to clarify the effect of AURKA on gastric cancer." (PMID 27121204, 2016). "Additionally, to confirm the role of AURKA, we established a subcutaneous gastric carcinoma model using the MGC-803 cell line and an orthotopic glioma model using the U87 EGFRvIII cell line." (PMID 27121204, 2016). "Furthermore, it has been shown that AURKA can regulate and suppress GSK3β kinase activity in gastric cancer cell lines." (PMID 25987188, 2015). "Similarly, overexpression of AURKA has been observed in early pre-neoplastic stages of gastric cancer in mouse models and human." (PMID 25987188, 2015). "This study evidences previously observed perturbations of the KRAS, ERBB2, EGFR, MET, PIK3CA, FGFR2 and AURKA genes in gastric cancer and suggests some of the targeted therapies approved or in clinical development would be of benefit to 11 of the 50 patients studied." (PMID 21781349, 2011). "Since the identification of proper markers that precisely predict aggressiveness of gastric cancer could improve the survival of these patients by managing their treatments, we asked if combined evaluation of AR and AURKA expression could introduce a proper prognostic marker." (PMID 31871591, 2019). "Finally, both AURKA and p27 were overexpressed in gastric cancer tissues." (PMID 30013101, 2018). "Thus, we showed that AURKA level, as an independent prognostic factor, was adversely associated with clinical prognosis, suggesting that the poor chemotherapy response in gastric cancer patients might be related to high AURKA expression." (PMID 28218735, 2017). "Moreover, immunohistochemical analysis showed that AURKA overexpression was correlated with tumor stage, lymph node metastasis and distant metastasis, but not with gender, age, tumor size, tumor site and tumor grading, suggestive of a role of AURKA in gastric cancer progression." (PMID 28218735, 2017).
gastric cancer (continued). "Our results provided evidence that AURKA expression correlated with cell response to chemotherapy and inhibition of AURKA might potentiate the efficacy of chemotherapeutic agent, such as doxorubicin for gastric cancer therapy." (PMID 28218735, 2017). "A strong and unexpected association emerged between AURKA and the Wnt modulator Rac GTPase‐activating protein 1 (RACGAP1) in a phenotype‐specific gastric cancer signaling network, that we validated by quantitative RT‐PCR in an independent, prospective cohort of gastric cancer patients." (PMID 26778597, 2016). "The findings suggest that AURKA might stimulate the generation of gastric cancer." (PMID 27121204, 2016). "Similarly, cell cycle kinase AURKA has been shown to be activated in gastric cancer and AURKA inhibitors in clinical development may have clinical benefit." (PMID 21781349, 2011). "An inverse relationship was observed between NKX6.3 expression and the levels of AurkA and TPX2 in human gastric cancer tissues." (PMID 39833908, 2025). "Among the downregulated miRNAs, predicted to bind AURKA 3′′ UTR, miR-4715-3p was significantly downregulated in human and mouse gastric cancers." (PMID 31740746, 2019). "In specific, depletion of endogenous UBE2C markedly reduces the level of phosphorylation AURKA via Wnt/β–catenin and PI3K/Akt signaling pathways and then suppressed the growth and metastasis of gastric cancer." (PMID 30914455, 2019). "Western blot analysis demonstrated overexpression of AURKA and phosphorylation of eIF4E in acquired and de novo CDDP‐resistant gastric cancer models." (PMID 28417568, 2017). "The western blot analysis indicated Survivin expression dramatically decreased in AURKA-depleted AGS and BGC823 gastric cancer cells, suggesting that AURKA positively regulated Survivin expression." (PMID 28218735, 2017). "Taken together, these results indicate that AURKA‐mediated acquired CDDP resistance is dependent on eIF4E and its downstream targets in AGS gastric cancer cells and suggest that targeting AURKA can be an effective therapeutic approach in CDDP‐resistant cells." (PMID 28417568, 2017). "Collectively, our new findings in this report add a significant novel perspective by showing that activation of AURKA–eIF4E axis is required for the induction of c‐MYC and HDM2 protein levels and CDDP resistance in gastric cancer cells." (PMID 28417568, 2017). "The physiological relevance of the regulation of Survivin by AURKA through the FOXP1–FBXL7 axis was further underscored by the significant positive correlations between AURKA and Survivin expression in gastric cancer patient samples." (PMID 28218735, 2017). "Together, these results suggest that AURKA targets FOXP1 to negatively regulate the expression of FBXL7, which can in turn negatively regulate Survivin protein levels in gastric cancer cells." (PMID 28218735, 2017). "We first screened a panel of gastric cancer cell lines for their sensitivity to CDDP and correlation with protein expression of AURKA, p‐eIF4E, eIF4E, c‐MYC, and HDM2." (PMID 28417568, 2017). "Taken together, our results strongly suggest that targeting AURKA using MLN8237 can induce tumor regression and achieve a therapeutic response in CDDP‐resistant gastric cancer." (PMID 28417568, 2017). "This is the first evidence of a direct link of AURKA and Wnt signaling via RACGAP1 in gastric cancer." (PMID 26778597, 2016). "Several studies have shown frequent overexpression of AURKA at the mRNA and protein levels in ESCC, EAC, and gastric cancers." (PMID 25987188, 2015). "Aurora kinase A (AURKA or STK15) located at 20q13, a region that is frequently amplified in gastric cancer, has been found overexpressed in stomach adenocarcinomas." (PMID 22606061, 2012). "Furthermore, three genes that we found to be amplified in serum-treated HEK293T cells (i.e., AURKA, RAE1, and ZFP64) are known to increase the resistance of pancreatic, colorectal, and gastric cancer cells to paclitaxel." (PMID 36289850, 2022).
gastric cancer (continued). "Targeting AURKA using MLN8237 may present a clinically relevant opportunity to treat CDDP‐resistant tumors and enhance the therapeutic response in patients with gastric cancer." (PMID 28417568, 2017). "Moreover, gastric cancer patients with high AURKA showed significantly poorer disease free survival (DFS, P=0.001) and overall survival (OS, P<0.001) compared with low AURKA expressing gastric cancer patients." (PMID 28218735, 2017). "Furthermore, studies have reported its dysregulation in two colon carcinoma cell lines (SW480 and Caco2) upon knockdown of the aurora kinase A (AURKA) gene, in papillary thyroid carcinoma, in hepatocellular carcinoma treated with cisplatin, and in gastric cancer." (PMID 37489459, 2023). "Furthermore, tRF-3019a (3′-tRF of tRNAAlaAGC) upregulation was reported to facilitate cell proliferation and invasion in gastric cancer by targeting FBXO47, while 5′-tRF-LeuCAG promoted both cell proliferation and cell cycle progression in non-small cell lung cancer through AURKA downregulation." (PMID 33291319, 2020). "The Aurora kinase A (AURKA) gene is frequently amplified and overexpressed in gastric cancer (GC)." (PMID 30174615, 2018). "Differential expression analysis revealed a significant downregulation of both AURKA and RACGAP1 in gastric cancer compared to noncancer controls." (PMID 26778597, 2016).